TNF (tumor necrosis factor)
Diseases named in the same sentence as TNF in open-access papers (continued):
Sharing a sentence is not in itself a finding about the gene and the disease.
depression (continued). "TNF-α is one of the most extensively investigated mediators in the studies on inflammatory factors in human epilepsy and depression." (PMID 38069144, 2023). "Further, they found that changes in IL-1RA and TNF-α at 2 months, as well as changes in three neural targets (negative influence circuit and positive influence circuit), correlated with changes in depression and anxiety symptoms at 6 months." (PMID 37387537, 2023). "Depression patients were found to have a pro-inflammatory profile in plasma, with significantly higher levels of TNF-α and CCL2 compared with controls." (PMID 37575572, 2023). "rTMS at 10 Hz to the left DLPFC can reduce the serum levels of IL-1β and TNF-α in elderly patients with refractory depression, and this change correlates with Hamilton Depression Rating Scale (HDRS) scores." (PMID 36624089, 2023). "Conversely, other studies have suggested that ECT has anti-inflammatory effects, and researchers performing ECT in patients with depression found reduced plasma levels of pro-inflammatory factors IL-6 and TNF-α and increased hippocampal volume." (PMID 36624089, 2023). "Ketamine, a novel rapid-acting antidepressant, reduces serum and cerebrospinal fluid IL-6, and serum IL-1β and TNF-α, while treating depression." (PMID 36838809, 2023). "Again, the picture of a decreased DA and increased inflammation, including TNFα, and reduced bilirubin, looks supportive of the possible beneficial anti-inflammatory action of pigment supply in depression." (PMID 37511235, 2023). "The results obtained confirm the involvement of the HPA axis, the system of neurotrophic factors (GDNF, BDNF), and inflammation (TNF-α) in the pathogenesis of epilepsy and depression." (PMID 38069144, 2023). "A separate investigation demonstrated that administering TNF-α induced symptoms of depression in mice, including cognitive decline and reduced social engagement." (PMID 37692303, 2023). "Secondary outcomes to be assessed are the severity of co-morbid depression and anxiety symptoms; the serum levels of IL-1β, IL-6 and TNF-α; changes in ERP and fecal microbiota content." (PMID 38051740, 2023). "After exercise intervention, the plasma levels of IL-1β, IL-6, and TNFα in patients with depression were significantly reduced, and depressive symptoms were improved." (PMID 37511879, 2023). "The concentrations of proinflammatory cytokines, like TNF-α, IL-1β and IL-6 were significantly higher in UC patients with symptoms of anxiety/depression." (PMID 36906523, 2023). "In line with this, the monoclonal antibody infliximab, a TNF-α functional antagonist, lowers symptoms of depression in patients with signs of inflammation, but is ineffective in patients with resistant depression." (PMID 37298431, 2023). "The proinflammatory cytokines, interleukin-1β(IL-1β) and tumor necrosis factor (TNF) have been implicated to play a major role in driving sickness behavior, including lethargy, depression, anorexia, fever, and cognitive impairment." (PMID 36918973, 2023). "The assessment of hypothalamic inflammatory responses induced by LPS stress involved the detection of the three inflammatory cytokines TNF-α, IL-1β, and IL-6 that play crucial roles in the pathogenesis of depression." (PMID 38062440, 2023). "In bipolar depression, IL-6 seems to be the predominant cytokine, IL-4 dominates in the euthymic state, and IL-2, IL-4, and IL-6 are prevalent in the manic state, while patients with unipolar depression mainly have elevated TNF-α, IL-6, and sIL-2R." (PMID 37510730, 2023). "The direct effect c′ was not statistically significant, suggesting that gratitude was unrelated to depression after including emotional support and TNF-α in the model." (PMID 37213708, 2023). "The results show a pro-inflammatory profile in plasma of depression patients, with increased TNF-α and CCL2, as well as significant correlations between the levels of different pro-and anti-inflammatory mediators." (PMID 37575572, 2023).
depression (continued). "Celecoxib treatment only improved peripheral IL-6 levels in depression and TNF-alpha levels in mania, but these are only single clinical studies on these markers." (PMID 37240605, 2023). "For example, preclinical studies showed that Knockout (KO) mice with TNF-α receptor 1 or 2 (TNFR1-2 KO) showed increased depression-like behaviors compared to wild-type mice while lateral ventricle injection of TNF-α in mice can induced mood disorders." (PMID 37273278, 2023). "Non-steroidal anti-inflammatory drugs (NSAIDs) and pharmacological inhibitors of specific cytokines like tumor necrosis factor α (TNFα) reduce depression scores." (PMID 37706039, 2023). "In contrast, the time course of the effects of COMBO on anxiety and depression in IBS paralleled an anti‐inflammatory effect as indicated by a reduction in circulating levels of TNF‐α." (PMID 36178333, 2023). "For example, medical illnesses that cause increases in inflammatory factors such as interleukin-6 (IL-6), tumor necrosis factor-α (TNF-α), and C-reactive protein (CRP) increase the risk for depression." (PMID 37840796, 2023). "Depression-related increases in pro-inflammatory cytokines, such as IL-6 and TNF, can, on one hand, further stimulate HPA and glucocorticoid release." (PMID 38067176, 2023). "The onset of “leaky gut” can trigger an inflammatory response, resulting in symptoms such as lethargy, depression, anorexia, and social withdrawal through the modulation of pro-inflammatory cytokines (TNF-a, IL-6, IL-1B)^142." (PMID 37375546, 2023). "On the other hand, in individuals with treatment-resistant depression, a rise in TNF-α levels was positively correlated with the antidepressant effect of a 12-week aerobic exercise." (PMID 37398548, 2023). "For example, high concentration of proinflammatory cytokines TNF‐alpha and IL‐6 were found in patients with major depression and clinical trials have indicated beneficial effects of anti‐inflammatory medications on major depression symptoms." (PMID 36573693, 2023). "Several meta-analyses have shown an increase in serum TNF-α and other proinflammatory cytokines in people suffering from depression." (PMID 36331794, 2023). "Increased inflammatory markers were measured in patients with major depressive disorder: IL-1β, IL-6, TNF-α, and CRP." (PMID 36899845, 2023). "The levels of pro-inflammatory cytokines (such as IL-6, TNF-α) were significantly increased in the serum of patients with depression." (PMID 37305539, 2023). "Numerous lines of clinical and translational research demonstrate the link between depression and heightened immune activation through increased numbers of proinflammatory cytokines such as IL-6, and TNF-α." (PMID 37398548, 2023). "Previous studies found that plasma TNF-α level was positively correlated with cognitive impairment, depression, and disability in PD patients, and it was also positively correlated with anxiety, age, and disease duration." (PMID 36875766, 2023). "Previous studies have shown that intraperitoneal injection of LPS leads to the production of IFN-γ and TNF-α in the mouse brain, and these two inflammatory factors have been shown to play an important role in LPS-induced depression-like behavior." (PMID 37292216, 2023). "According to extensive reports, high levels of pro-inflammatory and inflammatory markers impacted the inflammatory response to depression, namely, interleukin-1(IL-1), IL-18, IL-6, tumor necrosis factor-α (TNF-α), IFN-γ, and C-reactive protein (CRP)." (PMID 37090985, 2023). "Clinically, in comparison with healthy controls, patients with major depressive disorder have significantly higher levels of proinflammatory cytokines such as IL-6, TNFα, 8-OHdG, and F2-isoprostanes." (PMID 37599784, 2023). "We also developed a scoring system to assess the IBD-related depression and predict clinical response to anti-TNF- therapy, with a higher D. score suggesting more inflammation and worse reaction to biological therapies." (PMID 36923403, 2023).
depression (continued). "Meta-analyses of clinical studies have indicated a strong indication of pro-inflammatory cytokine involvement in depression, as demonstrated by higher concentrations of IL-6 and TNFα in the blood of depressed patients as compared to controls." (PMID 37485386, 2023). "All these findings suggest that upregulation of SIRT1 inhibits the levels of inflammatory factors such as GSK3β, TNF-α, and NF-κB to suppress the inflammatory response and exhibit anti-inflammatory effects, thereby improving depression-like behaviors." (PMID 37239191, 2023). "Levels of proinflammatory cytokines in peripheral blood were shown to be significantly increased in patients with major depressive disorder, such as IL-6, TNF-α and IL-1β." (PMID 37808199, 2023). "In our study, the TNF-α level in the depression group was higher in the active disease group than in the remission group." (PMID 37916198, 2023). "The CH–BS drug pair can reduce the generation of peroxidation products and down-regulate NLRP3 inflammasome expression, IL-1β, IL-6, and tumor necrosis factor (TNF)-α secretion to treat depression by combating inflammatory response and oxidative stress damage." (PMID 37109699, 2023). "In contrast, in a model of depression induced by tumor necrosis factor alpha (TNF‐α), IL‐1β expression in the hippocampus and reduced neurogenesis in dentate gyrus were observed." (PMID 37031383, 2023). "It has been suggested that pro-inflammatory cytokines (e.g., tumor necrosis factor, interleukin (IL)-1, IL-6, and IL-18) participate in the pathogenesis of RA and the development of depression in patients with RA." (PMID 36835939, 2023). "The pathophysiology of depression is thought to be mediated by TNFα signaling through the binding to its receptor TNFR1." (PMID 37511235, 2023). "TNF-α drugs are preferred over other biologic drugs and further studies have analyzed depression or anxiety levels among these patients and demonstrated that TNF-α antagonist-treated patients showed an improvement in mental state." (PMID 37046559, 2023). "Patients with major depression have been repeatedly observed to have activated inflammatory pathways, as manifested by increased proinflammatory cytokines such as TNF-α and IL-1β." (PMID 38259687, 2023). "In agreement, Infliximab, as a TNFα neutralizing antibody, can alleviate depressive symptoms in patients with treatment-resistant depression and elevated inflammatory markers." (PMID 37511235, 2023). "The inflammatory markers TNF-α and IL-6 are also higher in the blood of individuals with major depression, and generalized anxiety disorder (GAD)." (PMID 37706039, 2023). "Patients with SSRI-resistant depression have significantly higher production of the peripheral pro-inflammatory cytokines IL-6 and TNF-α compared to normal controls." (PMID 37700748, 2023). "Age-related chronic low-grade inflammation characterized by elevated levels of IL-6 and TNF-α has been reported as an important factor in the occurrence of sarcopenia and the development of depression." (PMID 37920543, 2023). "The evaluation of 292 individuals with major depression treated with fluoxetine for at least 6 weeks showed decreased levels of IL-1β, IL-6, or TNF-α at the end of the antidepressant treatment." (PMID 37242611, 2023). "Globally, we show that depression patients have increased systemic inflammation, reflected on increased plasma levels of TNF-α and CCL2, increased TNF-α mRNA levels in PBMCs, and dysregulated expression of key and inflammation-related miRNAs in PBMCs." (PMID 37575572, 2023). "Our findings suggest exploring new treatments for depression targeting TNF-α and MCP-4-mediated inflammatory pathways." (PMID 37967104, 2023). "In a randomized trial of participants with treatment-resistant depression, the TNFα inhibitor infliximab reduces depression scores, but only in the subpopulation of patients displaying elevation of the inflammatory marker C-reactive protein." (PMID 37706039, 2023).
depression (continued). "The impact of pro-inflammatory cytokines such as TNF-α, IL-1β, IL-6, and IL-8 on depression has been widely studied." (PMID 38025419, 2023). "TNF-α produces a powerful acute effect on degenerating brain function and correlates with the severity of disease-induced brain dysfunction, including depression, delirium and postoperative cognitive dysfunction." (PMID 38082215, 2023). "Researchers have proven that intestinal barrier destruction in depression is related to an increase in proinflammatory factors like LPS and TNF-α and IL-1β." (PMID 37025378, 2023). "We demonstrated that IBA1+ cell densities and TNFα are increased in the mPFC of vulnerable rats, which display increased anxiety- and depression-like behavior following 7 days of social defeat in the resident-intruder paradigm." (PMID 37706039, 2023). "Patients with depression present higher blood concentrations of pro-inflammatory cytokines, including tumor necrosis factor-α (TNF-α), interleukin 1β (IL-1β), IL-6, and other proteins such as C-reactive protein during the acute phase." (PMID 37199575, 2023). "Patients with major depression have significantly higher plasma concentrations of the cytokines TNF-α and IL-6 than controls." (PMID 36949894, 2023). "Patients with depression usually have higher concentrations of pro-inflammatory factors such as TNF-α and IL-6 than healthy controls." (PMID 37492068, 2023). "Compared to the remission group, there was a significantly higher level of TNF-α in the depression group (11.45 pg/ml vs. 9.69 pg/ml, p-value 0.006)." (PMID 37916198, 2023). "Maternal immune activation was shown to result in anxiety- and depression-like behaviors, cognitive impairment, and increased levels of proinflammatory cytokines, including interleukin (IL)-1β, IL-6, and tumor necrosis factor-alpha (TNF-α) in offspring." (PMID 37560531, 2023). "Pearson correlations between anxiety-/depression-/cognition deficit-like behaviors and the levels of inflammatory factors (IL-1β, TNF-α, and IL-6) in the hippocampus [r (p)]." (PMID 37560531, 2023). "Sustained stress exposure in IBS can result in HPA axis “fatigue” or blunting, glucocorticoid‐resistance, and an increase in systemic proinflammatory cytokines including TNF‐α contributing to the neuroinflammation manifested in depression." (PMID 36178333, 2023). "For example, peripheral delivery of a TNF-α antagonist was shown to alleviate depression symptoms in patients with elevated inflammatory biomarkers." (PMID 37699900, 2023). "The direct effect c′ was not statistically significant, suggesting that gratitude was unrelated to depression after including perceived stress and TNF-α into the model." (PMID 37213708, 2023). "For example, long-term corticosterone treatment significantly increased the mRNA levels of IL-1β, IL-6, and TNF-α in the hippocampus and hypothalamus, which in turn increased the anxiety-and depression-like behaviors in mice." (PMID 37168717, 2023). "An increase of IL6, IL-1, IL-17, and TNFα in peripheral blood related to anxiety and depression compared to healthy controls." (PMID 37916198, 2023). "The TNFα inhibitor infliximab reduces depression scores, but only in a subpopulation of individuals with higher levels of the inflammatory marker C-reactive protein." (PMID 37706039, 2023). "Some inflammatory markers interact with early life stress and can predict depression, such as TNF-α and IL-1β." (PMID 37700748, 2023). "Numerous evidence suggests that proinflammatory cytokines, such as interleukin (IL)-6, IL-1β, and tumor necrosis factor alpha (TNF-α), are elevated in individuals with depressive disorder." (PMID 37600668, 2023). "High concentrations of IL-1β and TNF-α have recently been observed to be related to the early onset of depressive disorder." (PMID 37834806, 2023).
depression (continued). "Lactococcus can reduce depression syndrome by reducing the levels of reactive oxygen species, tumor necrosis factor-α, and interleukin-1β in the hippocampal tissues of these animals and changing the fecal lactic acid bacteria content." (PMID 37189686, 2023). "The first study was published twenty years ago, and it has been reported recently that patients suffering from depressive disorder are characterized by increased concentrations of IL-1β, IL-6, and TNF-α compared to controls." (PMID 37834806, 2023). "In diabetes, the development of depressive disorder is related to hyperglycemia and an increase in the circulating pro-inflammatory cytokines IL-1β, IL-6, and TNF-α, known as low-grade inflammation." (PMID 37892186, 2023). "Other studies also showed that inflammatory factors such as IL1β, TNF‐α, and Tlr‐4 are involved in the development of depressive disorders which can be hindered by bioactive natural compounds in animal models." (PMID 36655100, 2023). "This has been supported by meta-analyses showing high levels of the same proinflammatory cytokines like RA (IL6, IL1β, and TNFα) in the peripheral blood of patients with depression compared with controls." (PMID 36422176, 2022). "Further, elevated levels of TNF-α, IL-6 (episode of depression), and IL-23 (episode of mania) were reported in BD." (PMID 34791253, 2022). "For instance, in colorectal cancer patients, serum IL‐1β, IL‐6, interleukin‐8 (IL‐8), and TNF‐α are positively correlated with increased anxiety and depression." (PMID 34697903, 2022). "In a clinical study on elderly patients with refractory depression, serum levels of IL-1β and TNF-α were decreased after rTMS treatment." (PMID 35392634, 2022). "Data consistently demonstrates that a subset of patients with depression show elevated levels of inflammatory biomarkers including Interleukin-6 (IL-6), Interleukin-1Beta (IL-1β), Tumour Necrosis Factor-alpha (TNF- α) and CRP." (PMID 35146459, 2022). "To conclude, serum TNF‐α, IL‐1β, and IL‐17 levels are highly expressed, which are closely related to elevated anxiety and depression risks to some extent in NSCLC survivors." (PMID 34697903, 2022). "In particular, IDO has been reported to catalyze the production of kynurenine from tryptophan in the brain, causing neuroinflammation, depression, and cognitive dysfunction by activating pre-inflammatory cytokines (IFN-γ, TNF-α, IL-1, and IL-6)." (PMID 35719088, 2022). "Exposure to immobilization stress (IS) or social defeat induces depression with neuroinflammation through the upregulated expression of interleukin (IL)-6 and tumor necrosis factor (TNF)-α in mice, resulting in gut inflammation and dysbiosis." (PMID 35631220, 2022). "Stress and depression are related to high levels of proinflammatory biomarkers like interleukin (IL): IL-1β, IL-1α, IL-6, tumor necrosis factor-α (TNF-α), interferon-γ and C-reactive protein (CRP)." (PMID 36078738, 2022). "The levels of neuropeptide Y (NPY), testosterone (T), and IL-1β, IL-6, TNF-α, IL-10, and IL-4 in the peripheral blood plasma of normal people, patients with depression, and patients with DCMI were measured." (PMID 35432561, 2022). "In the prefrontal cortex of a rat model of depression, interleukin (IL)-1β, IL-6, tumor necrosis factor-α (TNF-α), microglial activation, and NF-κB signaling are upregulated." (PMID 35496318, 2022). "Based on univariate analysis of 15 antiviral or proinflammatory cytokines, depression was associated with elevated MCP-1 and decreased TNFα, whereas G-CSF was significantly elevated in those with a history of neuroinvasive WNV." (PMID 35745504, 2022). "In similar studies, patients with depression were found to have elevated levels of proinflammatory cytokines, including tumor necrosis factor-α (TNF-α), interleukin 1β (IL-1β), IL-6, and C-reactive protein (CRP)." (PMID 35054853, 2022).